HINT3 (histidine triad nucleotide binding protein 3)
Description:
Exhibits adenosine 5'-monophosphoramidase activity, hydrolyzing purine nucleotide phosphoramidates with a single phosphate group such as adenosine 5'monophosphoramidate (AMP-NH2) to yield AMP and NH2. Hydrolyzes lysyl-AMP (AMP-N-epsilon-(N-alpha-acetyl lysine methyl ester)) generated by lysine tRNA ligase. Hydrolyzes 3-indolepropionic acyl-adenylate and fluorogenic purine nucleoside tryptamine phosphoramidates in vitro.
Synonyms: FLJ33126; HINT4
Tractability: PROTAC: ubiquitination databases record sites on it; its protein half-life has been measured.
Gene: Protein-coding gene on chromosome 6 (125,956,733 to 125,980,244, forward strand). Ensembl gene ENSG00000111911.
Subcellular location: Cytoplasm; Nucleus
Subcellular location (Human Protein Atlas): Mitochondria; Nucleoli; Cytosol
Gene Ontology:
Molecular function: adenosine 5'-monophosphoramidase activity; identical protein binding; catalytic activity
Cellular component: cytoplasm; mitochondrion; nucleus
Genetic constraint (gnomAD): Loss-of-function variants: 9 observed, 8.17 expected, observed/expected ratio (o/e) 1.1, 90% interval 0.66 to 1.78. That is too few expected variants to judge how well the gene tolerates losing a copy. Missense variants: 108 observed, 124.01 expected, observed/expected ratio (o/e) 0.87, 90% interval 0.74 to 1.02. Synonymous variants: 43 observed, 44.52 expected, observed/expected ratio (o/e) 0.97, 90% interval 0.76 to 1.25.
Homologues: Orthologues: chimpanzee HINT3 (99% identical), macaque HINT3 (92% identical), pig HINT3 (73% identical), guinea pig HINT3 (68% identical), rat Hint3 (63% identical), mouse Hint3 (62% identical), tropical clawed frog hint3 (53% identical), zebrafish hint3 (48% identical), Drosophila melanogaster CG34015 (30% identical), Drosophila melanogaster CG15362 (27% identical), Caenorhabditis elegans hint-3 (26% identical). Paralogues in human: APTX (25% identical).
Diseases named in the same sentence as HINT3 in open-access papers:
HINT3 is named in the same sentence as 12 diseases in open-access papers, as found by Europe PMC text mining. Sharing a sentence is not in itself a finding about the gene and the disease. The quoted sentences say what the papers report.
breast carcinoma (2 papers, 2025). "There is a paucity of literature on the relevance of HINT3 to disease, but existing reports indicate high expression in breast cancer, where it strongly correlates with mortality, and in hepatocellular carcinoma, where it is associated with apoptosis-resistance in the face of serum starvation." (PMID 40376595, 2025). "recently reported that HINT3 inhibits the activation of the PTEN/AKT/mTOR signaling pathway, suppressing the proliferation, growth, migration, and tumor development of MCF‐7 and MDA‐MB‐231 breast cancer cells." (PMID 40755357, 2025).
endometriosis (1 paper, 2025). The growth of functional endometrial tissue in anatomic sites outside the uterine body. "Furthermore, the identification of upregulated genes, such as SIRT1, SBDS, SRF, SPN, P2RX1, TEAD3, and SLITRK3, alongside downregulated genes, including KIF22, KIF25, GAS2L2, and HINT3, highlights a broad transcriptional reprogramming within endometriosis-affected tissues." (PMID 41516028, 2025). "In contrast, some genes were significantly downregulated in endometriosis patients, among others KIF22, KIF25, GAS2L2, and HINT3." (PMID 41516028, 2025).
myocardial ischemia (1 paper, 2025). A disorder of cardiac function caused by insufficient blood flow to the muscle tissue of the heart. "HINT3 expression declines after myocardial ischemia‐reperfusion injury." (PMID 40755357, 2025). "In this study, we utilized a mouse model of myocardial ischemia‐reperfusion injury and a cellular model of oxygen‐glucose deprivation/reoxygenation (OGD/R) to investigate the role of HINT3 in reperfusion injury." (PMID 40755357, 2025).
tumor (3 papers, 2022 to 2025). "APOOL and HINT3 are tumor-related genes that were first discovered in this study as new prognostic markers for BC, but the mechanism of these genes in BC remains to be clarified." (PMID 38245717, 2024). "KRAS-Mut tumors showed significant upregulation of tumor migration (TGFBR2-S553 and EPHB3) and PI3K/AKT activation (PIP4K2C and PIK3R1), while the KRAS-WT group was enriched in immune regulation (TAP1/2, IFITM1, and IFIH1-S301) and cellular metabolism (DGAT1 and HINT3)." (PMID 35836817, 2022).
cardiovascular diseases (1 paper, 2025). "By constructing a mouse myocardial I/R injury model and OGD/R model, we have expanded the understanding of HINT3 in cardiovascular diseases and mitochondrial function." (PMID 40755357, 2025). "It remains unclear whether HINT3, like its family members, contributes to the pathogenesis of cardiovascular diseases or participates in mitochondrial regulation." (PMID 40755357, 2025). "Studies suggest that HINT2 mitigates pressure‐overload‐induced cardiac remodeling by affecting the activity and assembly of mitochondrial complex I. However, research on HINT3, a family member of HINT1 and HINT2, is scarce, especially in the context of cardiovascular diseases." (PMID 40755357, 2025).
HINT3 also shares sentences with these, for which no sentence is quoted: cancer (1 paper); endothelial dysfunction (1); heart failure (1); hepatocellular carcinoma (1); myocardial infarction (1); pulmonary arterial hypertension (1); Right ventricular hypertrophy (1).